CXCL12 (C-X-C motif chemokine ligand 12)
Diseases named in the same sentence as CXCL12 in open-access papers (continued):
Sharing a sentence is not in itself a finding about the gene and the disease.
infection (continued). "First, we demonstrated that CXCL12/SDF-1 potently prevented the accumulation newly reverse-transcribed HIV proviral DNA from the genomic viral RNA, a mandatory process required for productive infection." (PMID 26097474, 2015). "CXCL12 sequestration was dependent on viral gene expression, as perinuclear accumulation of the chemokine was not seen after infection with UV-inactivated virus." (PMID 23116176, 2012). "UV-inactivated HCMV did not induce the perinuclear sequestration of CXCL12 seen after infection with wild-type virus." (PMID 23116176, 2012). "The goal of this study was to determine whether host factors such as the chemokine axis CXCL12/CXCR4, which notably participates in the control of immune surveillance, can influence the outcome of the infection." (PMID 22511975, 2012). "Infection with HCMV did not significantly alter mRNA expression of CXCL12 at any timepoint analyzed." (PMID 23116176, 2012). "CXCL12 expression was not increased in response to infection with 7.13 or 26695 strains of H. pylori." (PMID 22216156, 2011). "Although IAV-PR8 infection failed to increase blood neutrophil numbers or CXCL12 expression by endothelial cells, the involvement of the CXCL12/CXCR4 axis in regulating neutrophil, especially LDN, accumulation in the lungs and bone marrow deserves further investigation." (PMID 39773555, 2025). "CXCL12 transcripts were significantly upregulated in KSX-476 but not KSX-488 upon infection." (PMID 39386738, 2024). "In fact, CXCL12 expression, which was mediated by IL-1 at the CNS microvasculature, restricted entry of T cells at the BBB and prevented virus-specific CD8+ T cells from clearing WNV within the CNS parenchyma, resulting in enhanced mortality in a murine model of infection." (PMID 36992514, 2023). "Similarly, chemokines (e.g. CXCL1, CXCL2, and CXCL5) that play a pivotal role in neutrophil recruitment to sites of infection and injury were induced 2–3 orders of magnitude, whereas CXCL12/SDF‐1 and adhesion G‐protein coupled receptor F5 (ADGRF5, GPR116) expression was unaffected." (PMID 36151614, 2022). "Moreover, the naive T cells showed a significantly enhanced migration following E-30 infection + CXCL12 compared with the condition without infection." (PMID 31752904, 2019). "Very little or no infection-related effects were detected for SDF-1α (CXCL12) and IL-8 (CXCL8)." (PMID 30467502, 2018). "Similarly, B6.Rag2−/− mice showed no reduction of Cxcl12 mRNA accumulation after 4 weeks of infection compared to the ~50% reduction seen in wild-type mice." (PMID 30619317, 2018). "The B cell chemoattractant, CXCL13 was dramatically lower in aged as compared to juvenile animals, regardless of infection status whereas CXCL12 and CCL20, known dendritic cell (DC) chemoattractants, were much higher in mock and SARS-CoV infected aged animals (unpaired student T-test)." (PMID 24642138, 2014). "Furthermore, trans infection mediated by mature DC with R5 but not X4 virus is enhanced by CXCL12, the chemokine ligand for CXCR4." (PMID 24278768, 2013). "However, there was only a minor effect of HIBCPP-infection with EV30 on transepithelial T lymphocyte migration with or without the chemoattractant CXCL12." (PMID 23305147, 2013). "Thus, iBALT formation is complex and modulation in the levels of factors such as SDF-1α/CXCL12, CD30L/CD153 and MIP-3β/CCL19 by M3 may contribute to the formation of iBALT in context of MHV-68 infection in wood mice." (PMID 21445235, 2011). "X4LAI.04 infection of tissues treated with flagellin did not affect the release of CXCL12." (PMID 20862220, 2010). "Therefore, the role of Cxcl12/Cxcr4 signaling axis against infection may be not affected by the retention and/or migration of leukocyte population." (PMID 33013914, 2020).
infection (continued). "CXCL12 and CXCL16 are expressed by the ependyma and periventricular region irrespective of infection, paralleling the expression of CXCR4 and CXCR6 by brain-infiltrating T cells to regulate their migration to infectious foci to the ventricular barrier." (PMID 40581668, 2025). "Infection outcome 30 days p.i. did not modify CXCL12 expression in BALB/c mice, whereas C57BL/6 mice displayed more CXCL12 in their mesothelium." (PMID 22511975, 2012). "Second, using HIV-1 particles whose envelope glycoprotein was replaced by the one from vesicular stomatitis virus, which enables infection in a CD4- and coreceptor-independent manner, we proved that CXCL12/SDF-1 failed to inhibit the viral replication (occurring after viral entry)." (PMID 26097474, 2015). "Moreover, CXCL12 blockade did not affect the development of virus-specific memory CD4+ and CD8+ T cell responses in the blood or lungs when assessed on day 30 after SARS2-N501YMA30 infection." (PMID 39773555, 2025).
cardiovascular disease (29 papers, 2011 to 2025). "Air pollution, meanwhile,elevates cardiovascular disease risk by altering CXCL12 expression, andX chromosome variants significantly regulate sex differences in cardiovasculardisease incidence." (PMID 40776945, 2025). "The higher levels of CXCL12 in atherosclerotic lesions than in healthy vessel wall cells suggest that CXCL12 is associated with cardiovascular diseases." (PMID 37959416, 2023). "Many hot nodes in the PPI network are inflammatory factors, including IL8, IL1B, CXCL3, CXCL12, and HLA genes, which are associated with cardiovascular diseases." (PMID 30885136, 2019). "GWAS reported that SDF-1 gene (CXCL-12), which located on 10q11.1 and involved in progenitor cell proliferation, traffic, adhesion and regulates cell survival, associated with cardiovascular disease susceptibility." (PMID 28903360, 2017). "It is worth mentioning that genome-wide association studies revealed a significant association of two SNPs downstream of the CXCL12 gene with cardiovascular disease." (PMID 26300887, 2015). "However, more data are needed to confirm the role of CXCL12 and other chemokines as biomarkers in a specific population at high risk for cardiovascular disease, such as T2D subjects." (PMID 34987703, 2021). "In the future, the results of this research are expected to be used to develop precision treatment methods targeting the CXCL12 pathway and promote the application of precision medicine in cardiovascular diseases." (PMID 40421026, 2025). "In recent years, the chemokine Stromal cell-Derived Factor 1α (SDF1α or CXCL12) has been shown to play a role in cardiovascular diseases and to be a promising biomarker." (PMID 26544044, 2015). "Although the importance of CXCL12 in cardiovascular disease has been intensively studied, current findings once again suggest a double-edged role of this chemokine in ischemic heart and atherosclerosis." (PMID 26300887, 2015). "Upregulated CXCL2 expression and secretion may favor the development of cardiovascular diseases, while the fast increase of CXCL12 in peripheral blood platelets can be used as biomarker for cardiac injury." (PMID 34084749, 2021). "However, two roles have been proposed for CXCL12 in cardiovascular disease." (PMID 35668739, 2021). "Although recent studies have demonstrated that CXCL12/CXCR4 axis plays a critical role in lymphocytes and macrophages’ recruitment to the sites of injury in diverse cardiovascular diseases, while its effect in AF is unknown." (PMID 34453039, 2021). "Furthermore, the key genes identified by MCODE analysis, HP, CXCL12, COL3A1, and PECAM1, may also serve as candidate targets for cardiovascular disease diagnosis." (PMID 32612856, 2020).
hematological malignancies (14 papers, 2016 to 2026). "Beyond conferring survival advantages to malignant cells, the activated CXCL12/CXCR4/ACKR3 axis also enhances the invasiveness of hematological malignancies by regulating cell migration and conferring resistance to chemotherapy." (PMID 38920657, 2024). "The effects of anti-CXCL12/CXCR4 therapies have been most extensively studied in hematological malignancies, in which monoclonal CXCR4 targeting antibodies such as Ulocuplumab, have been tested with varying results." (PMID 33530455, 2021). "Ulocuplumab (BMS-936564/MDX1338) was shown to block CXCL12 binding to CXCR4-expressing cells, inhibiting CXCL12-induced migration and inducing apoptosis in different hematological malignancies." (PMID 33081391, 2020). "Notably, stromal cell‐derived factor‐1α (SDF‐1α), also known as chemokine CXCL12, is involved in the metastasis of many solid and hematological malignancies." (PMID 36632988, 2023).
immune diseases (11 papers, 2010 to 2026). "Also, it is likely that this will be exacerbated by a range of maternal inflammatory and immune diseases, many of which are known to be associated with enhanced levels of plasma CXCL12." (PMID 38300826, 2024). "CXCL12 is expressed in multiple tissues including the kidney and is altered during pathophysiological responses including immune diseases." (PMID 41531734, 2026).
kidney disease (11 papers, 2018 to 2026). "In contrast, CXCL12 exhibits a dual role in renal diseases; some studies have demonstrated that CXCL12 blockade increases podocyte numbers, reduces proteinuria, and promotes glomerular repair." (PMID 41601976, 2026). "Further studies are needed to identify CXCL12 formulations that may increase the efficacy of this therapy to treat more advanced kidney disease and to fully elucidate the mechanism, tissue and systemic dispersion, and duration of effect." (PMID 33748219, 2021). "Thus, whether CXCL12 exerts protective or injurious effects in renal disease appears to be highly dependent on the specific disease model and pathological stage, emphasizing the need for comprehensive evaluation in clinical settings." (PMID 41601976, 2026). "In the pilot study, recombinant CXCL12 treatment for cats with early CKD was safe and feasible in a general practice setting, and we measured changes in kidney disease stage progression, USG, serum creatinine, and SDMA in both groups." (PMID 33748219, 2021). "Clinical Pilot: 14 client-owned cats with potential early kidney disease received a single-treatment, bilateral intra-renal injection of 200 ng CXCL12 (n = 7), or received no injection (n = 7)." (PMID 33748219, 2021). "The ideal candidates for CXCL12 therapy may be in the early stages of kidney disease, which can have subtle or no clinical signs, therefore, elevating the value of routine wellness screening and early disease detection." (PMID 33748219, 2021).
neurodegenerative disease (11 papers, 2018 to 2025). A disorder of the central nervous system characterized by gradual and progressive loss of neural tissue and neurologic function. "Furthermore, a positive correlation was found between α-synuclein, a protein involved in the regulation of dopamine release and associated with neurodegenerative disease, and CXCL12 in the postmortem brain tissue of PD patients." (PMID 34216357, 2022). "Brain lesions caused by trauma, infection, or neurodegenerative disease result in the localised production of chemoattractants CCL21 and CX3CL1 by neurons and astrocytes, and MCP-1/CCL2 and SDF-1α/CXCL12 by activated microglia adjacent to the lesion." (PMID 36359810, 2022). "We then correlated CXCL12 levels with neurodegenerative disease biomarkers, including ubiquitin carboxyl-terminal esterase L1, total tau, phosphorylated tau 181, amyloid-β, α-synuclein and NEFL." (PMID 34648304, 2021). "Finally, to learn about disease specificity of CXCL12 in sALS, the CSF of other neurodegenerative diseases, including SMA (n = 13), AD (n = 19), FTD (n = 39), and MS (n = 30) was analyzed." (PMID 33213069, 2020). "Of interest, the CXCR7 inhibitor CCX771 was recently described to interfere with CXCL12-directed migration of CXCR7-positive CD14+ CD16+ monocytes of HIV-infected people into the CNS, which can result in a neurodegenerative disease termed NeuroAIDS." (PMID 29560468, 2018). "Several studies have demonstrated that there is a powerful correlation between the dysregulated CXCR4 and neurodegenerative diseases including AD, and the inhibition of CXCR4/CXCL12 signaling pathways is able to alleviate glutamate release mediated toxic cascade and neuronal apoptosis." (PMID 36569892, 2022).
adenocarcinoma (9 papers, 2009 to 2022). A common cancer characterized by the presence of malignant glandular cells. "They observed that the expression levels of Bcl-2 and bcl-xl in the adenocarcinoma cell line increased with CXCL12 therapy and decreased with CXCR4 antagonist and JAK2 inhibitor therapy." (PMID 31718601, 2019). "Even on HFD, only 25% of CXCL12 KO mice had adenocarcinomas." (PMID 33753872, 2021). "The quantitative expressions of CXCL12 and CXCR4 messenger RNA (mRNA) were evaluated in 32 patients with adenocarcinoma-type CRC." (PMID 29887884, 2018). "On immunohistochemical staining using anti-human CXCR4 mouse monoclonal antibody (clone 44716) and anti-human/mouse CXCL12/SDF-1 mouse monoclonal antibody (clone 79018), DLBCL cells were positive for CXCR4 and adenocarcinoma cells were positive for CXCL12/SDF-1." (PMID 34187383, 2021). "Moreover, in intestinal adenomas and adenocarcinomas that occurred in APCΔ14/+, APCMin/+ or azoxymethane-treated wild-type mice (data not shown), CXCL12 expression was strongly reduced." (PMID 28418886, 2017).
Colorectal (9 papers, 2005 to 2022). "Thus, the eight gene panel (CXCL12, CK7, CDH1, CTNNB1, CD44v6, MUC16, TGFBR2 and HIF1A) can be a highly significant predictor of liver metastasis outcome independent of the standard prognostic criteria." (PMID 30383826, 2018).
heart diseases (9 papers, 2015 to 2024). "Paracrine factors, which are regarded as key regulator benefitting CDCs therapeutic effect in heart diseases, were highly expressed in iECDCs [chemokine (C-X-C motif) ligand 12 (CXCL12), VEGF, FGF, IGFBP4, etc.]." (PMID 35141286, 2021). "The chemokine Stromal cell-derived factor 1α (SDF1α, CXCL12) is currently under investigation as a biomarker for various cardiac diseases." (PMID 26544044, 2015). "MIF and CXCL12 are considered as a potential biomarker for heart diseases in patients with T2DM." (PMID 35663309, 2022). "ANXA2 also interacts with CXCL12 (SDF1), a BMP9-inducible protein in endothelial cells and a well-defined homing molecule identified for improved stem cell treatments in heart disease." (PMID 39430425, 2024). "Through big data analysis, we found that HBP family members, such as HP, CXCL12, COL3A1, PECAM1, and other highly correlated genes, play a role in heart diseases." (PMID 32612856, 2020).
inflammation (6 papers, 2017 to 2025). Aberrant reaction of the microcirculation characterized by movement of fluid and leukocytes from the blood into extravascular tissues. "In previous work, the neutraligand of CXCL12 was reported to reduce dendritic cell infiltration into the airways and to diminish airway eosinophilic inflammation in OVA-challenged asthmatic mice." (PMID 34118928, 2021). "The inflammatory-inducing effect of LPS was observed not only on cytokines but also on chemokines such as MCP1, MCP2, CXCL12, and RANTES proteins in in vitro models (human monocytes and murine macrophages); these chemokines are overexpressed in chronic intestinal inflammation." (PMID 40646731, 2025).
metabolic disorders (5 papers, 2019 to 2025). "Our study highlights the role of inflammation and specifically the role of CXCL12 as an exerkine functioning as a positive effector in the adaptive response of skeletal muscle to acute exercise in metabolic diseases." (PMID 36070371, 2022).
bacterial infections (4 papers, 2012 to 2025). "We showed that Cxcl12 was induced 12 hours after uropathogenic bacterial infection in mouse bladder." (PMID 41364520, 2025). "Bacterial infection of ductal cells also coincides with the fact that CXCL9, CXCL10, CXCL12, chemokines involved in lymphocyte trafficking, are predominantly expressed in the ductal epithelium adjacent to lymphoid infiltrates in SS." (PMID 32208441, 2020).
brain diseases (4 papers, 2013 to 2025). "This is in line with studies that report CXCL12/CXCR4 signaling improves cognitive performance in other models of brain disease, suggesting our results may also inform CNS therapeutic strategies more broadly." (PMID 40335156, 2025).
inflammatory myopathies (4 papers, 2019 to 2025). "The abundance of CXCR4, a chemokine receptor for ligand SDF1 (CXCL12), indicates inflammatory myopathy conditions." (PMID 30678732, 2019). "Collectively, in inflammatory myopathies, we demonstrate the muscular presence of molecular factors that are crucial for B cell survival, maturation, activation, and differentiation (BAFF) as well as for B-cell chemotaxis (CXCL-12 and 13)." (PMID 37731487, 2023). "Neither gene expression of CCR7 nor CXCR4 was elevated in ASyS or IMNM patients (an acute inflammatory myopathy serving as DC) compared to NDC, while CXCL12 expression was elevated in PL-7+ patients when compared to Jo-1+ patients." (PMID 35612662, 2022).
hematological neoplasms (3 papers, 2021 to 2024). "Due to its role in homeostasis of the HSC niche, CXCL12 is likely to play a key role in hematological tumors and their respective CSCs." (PMID 33530455, 2021). "All these findings may contribute to a better understanding of CXCL12’s potential mechanism and clinical relevance in both solid tumors and blood cancers." (PMID 34327063, 2021).
infectious disease (3 papers, 2016 to 2020). A disorder directly resulting from the presence and activity of a microbial, viral, or parasitic agent in humans. "This study did not however directly enumerate CXCL12-producing cells in BM, our observations here being the first reported instance of loss of these cells during infectious disease." (PMID 30619317, 2018).
psychiatric disorder (2 papers, 2016 to 2024). A disorder characterized by behavioral and/or psychological abnormalities, often accompanied by physical symptoms. "CXCR7 is a G-protein-coupled receptor and can interact with either CXCL11 or CXCL12 that has been implicated in various aspects of inflammation and psychiatric disorders." (PMID 38674048, 2024).
animal diseases (1 paper, 2005). "Availability of specific inhibitors of the CXCL12-CXCR4 interaction has allowed the demonstration of the involvement of CXCL12 in experimental animal diseases." (PMID 16277673, 2005).
colon polyps (1 paper, 2022). "The colon polyps demonstrated decreased expressions in CCL5, CCL18, CCL19, CCL21, CXCL12, CXCL14 and CXCL13 genes in this research." (PMID 35486660, 2022).
connective tissue diseases (1 paper, 2025). "In connective tissue diseases like SLE and RA, CXCL12 facilitates the migration of immune cells to inflammatory sites, while CCL5 amplifies the recruitment of T cells and monocytes, promoting chronic inflammation and tissue damage." (PMID 39860439, 2025).
neuromuscular disease (1 paper, 2023). "Human primary myotubes derived from individuals without a neuromuscular disease produced BAFF and CXCL-12 mRNA and protein upon exposure to proinflammatory cytokines." (PMID 37731487, 2023).
CXCL12 also shares sentences with these, for which no sentence is quoted: multiple myeloma (52 papers); acute myocardial infarction (16); retinopathy (9); diabetic retinopathy (8); proliferative diabetic retinopathy (7); dilated cardiomyopathy (6); gastrointestinal tumor (6); idiopathic pulmonary fibrosis (6); medulloblastoma (6); synovitis (6); acute kidney injury (5); hematological tumor (5); non-Hodgkin lymphoma (5); acute coronary syndrome (4); acute pancreatitis (4); atrial fibrillation (4); heart (4); knee osteoarthritis (4); myelodysplastic syndrome (4); myeloid leukemia (4); skin cancer (4); unstable angina (4); brain cancer (3); Burkitt lymphoma (3); co-infection (3); demyelination (3); diabetic cardiomyopathy (3); Encephalopathy (3); joint diseases (3); measles (3).
A further 237 diseases each share a sentence with CXCL12 in 3 papers or fewer.